BPIFA1 (BPI fold containing family A member 1)
Diseases named in the same sentence as BPIFA1 in open-access papers (continued):
Sharing a sentence is not in itself a finding about the gene and the disease.
chronic sinusitis (2 papers, 2018 to 2022). "It was found that sinusitis positive for Pseudomonas aeruginosa bacterial culture is associated with decreased BPIFA1 in the sinus mucosa, which may serve as a diagnostic tool to assess expression of BPIFA1 in patients." (PMID 30255091, 2018). "This decrease in BPIFA1 expression in sinus or upper airway mucosa also leads to repeated infection of the upper airway, including middle ear infection and sinusitis." (PMID 30255091, 2018).
middle ear infection (2 papers, 2015 to 2018). "Current evidence of the direct relationship between middle ear infection and BPIFA1 is lacking." (PMID 30255091, 2018).
airway allergies (1 paper, 2015). "Interleukin 13 (IL-13), a cytokine predominately secreted by TH2, has been found to contribute to airway allergies and to suppress BPIFA1 expression in nasal epithelial cells." (PMID 26646664, 2015). "Interleukin 13 (IL-13), predominately secreted by T helper 2 (TH2) cells, has been found to contribute to airway allergies and suppress BPIFA1 expression in nasal epithelial cells." (PMID 26646664, 2015).
airway hyperresponsiveness (1 paper, 2017). "Our data suggest that BPIFA1 deficiency in asthmatic airways promotes Orai1 hyperactivity, increased ASM contraction and airway hyperresponsiveness." (PMID 28165446, 2017).
chronic periodontitis (1 paper, 2017). A chronic inflammatory process that affects the tissues that surround and support the teeth. "Therefore, research is required to investigate the expression level of salivary BPIFA1 in patients with chronic periodontitis with T2DM." (PMID 29109737, 2017). "Chronic periodontitis is caused by Gram-negative periodontal bacteria containing LPS and may lead to the changes in BPIFA1 concentration in saliva." (PMID 29109737, 2017).
co-infection (1 paper, 2023). "BPIFA1 is an important component of innate immunity, the upregulation hints at co-infection of bacteria." (PMID 37949875, 2023).
COVID-19 (1 paper, 2023). A disease caused by infection with severe acute respiratory syndrome coronavirus 2. "Intriguingly, differentially expressed genes shared between non-survivors of COVID-19 and HAP/CAP included genes associated with both innate immunity (e.g., BPIFA1) and adaptative immunity (e.g., IGHA1)." (PMID 37949875, 2023). "BPIFA1 participates also in the inflammatory response of the upper respiratory tract and stimulates the migration of macrophage and neutrophils, agreeing well with the enrichment of neutrophil chemotaxis and migration process in the COVID-19 non-survivors." (PMID 37949875, 2023).
mucositis (1 paper, 2020). Mucositis is inflammation and damage of the mucous membranes lining the mouth and other parts of the gastrointestinal (GI) tract.
Obesity (1 paper, 2024). Accumulation of substantial excess body fat. "In the process of integrating multi-omics correlation analysis, we identified a set of biomarkers with well-interconnected networks implicated in obesity, such as BPIFA1, BPI, SAA1, PDE1C, Deoxycholic acid, Phthalic anhydride, DL-Alanine, p_Firmicutes, g_Intestinimonas, and g_Turicibacter." (PMID 39609876, 2024). "In this study, the BPIFA1 gene is increased in the obesity group." (PMID 39609876, 2024).
periodontitis (1 paper, 2017). An acute or chronic inflammatory process that affects the tissues that surround and support the teeth. "In the moderate periodontitis group, BPIFA1 was significantly lower than in the severe periodontitis group (P = 0.024)." (PMID 29109737, 2017). "In subjects with severe periodontitis, the level of BPIFA1 was significantly lower than in those with moderate and mild periodontitis." (PMID 29109737, 2017). "Those with severe periodontitis had significantly lower levels of BPIFA1 than those with mild periodontitis (P = 0.021) and moderate periodontitis (P = 0.002)." (PMID 29109737, 2017). "In T2DM individuals with severe periodontitis (median = 188.05), the level of BPIFA1 was significantly lower than in those NDM individuals with severe periodontitis (median = 1441.96)." (PMID 29109737, 2017). "Comparison between the T2DM and NDM groups revealed that the NDM group with moderate periodontitis had significantly lower levels of BPIFA1 than the T2DM group with moderate periodontitis (P = 0.004)." (PMID 29109737, 2017). "Although the concentration of BPIFA1 was lower in the moderate periodontitis group than that in the mild periodontitis group, the differences were not statistically significant (P > 0.05)." (PMID 29109737, 2017). "However, in T2DM subjects with severe periodontitis, the body might become recalcitrant to BPIFA1 during inflammation." (PMID 29109737, 2017). "In those T2DM subjects with mild and moderate stages of periodontitis, it might be that augmented systemic inflammation may be able to reach the stimulation threshold of salivary BPIFA1, which consequently leads to an increase in salivary BPIFA1 concentration through feedback mechanisms." (PMID 29109737, 2017). "In addition, salivary BPIFA1 might reflect regulation of the inflammatory immune response in periodontitis subjects through the production of salivary TNF-α." (PMID 29109737, 2017). "In order to compare the differences of salivary BPIFA1, TNF-α, and IL-6 concentrations among T2DM/NDM patients with periodontitis at different stages, we further divided the subjects into eight subgroups." (PMID 29109737, 2017). "In T2DM subjects with nonperiodontitis or severe periodontitis, the level of BPIFA1 was significantly lower compared with that of NDM." (PMID 29109737, 2017). "Conversely, in NDM groups, we found that the expression level of BPIFA1 was significantly higher in nonperiodontitis or severe periodontitis subjects compared with those in the moderate periodontitis group." (PMID 29109737, 2017). "When the T2DM and NDM groups were compared with each other, the level of BPIFA1 was significantly lower in the T2DM group without periodontitis (median = 110.00) compared with the NDM group without periodontitis (median = 879.89)." (PMID 29109737, 2017). "During severe periodontitis in NDM individuals, aggravated inflammation might be able to reach the stimulation threshold of BPIFA1, which leads to an increase in salivary BPIFA1 concentration." (PMID 29109737, 2017). "In the NDM group, the concentration of BPIFA1 in those with nonperiodontitis was significantly higher than in those with moderate periodontitis (P = 0.019)." (PMID 29109737, 2017). "However, expression levels of salivary BPIFA1 decreased in the T2DM group in individuals with nonperiodontitis or severe periodontitis." (PMID 29109737, 2017). "However, in the T2DM group, the concentration of BPIFA1 was significantly lower in those with nonperiodontitis compared to those with mild periodontitis (P = 0.042) and moderate periodontitis (P = 0.005)." (PMID 29109737, 2017). "Therefore, we speculate that salivary BPIFA1 could be regarded as a potentially predictive biomarker of T2DM subjects especially those with severe periodontitis or nonperiodontitis." (PMID 29109737, 2017).
periodontitis (continued). "We demonstrated that BPIFA1 is present at significant concentrations in saliva and can be used as a sensitive biomarker of T2DM, especially in patients with severe periodontitis and nonperiodontitis." (PMID 29109737, 2017). "The reason might be that during moderate periodontitis in NDM subjects, inflammation may only be slight and may not reach the stimulation threshold of BPIFA1." (PMID 29109737, 2017). "BPIFA1 protein is rich in saliva and might be used as a potential predictive biomarker of T2DM, especially in patients with severe periodontitis and nonperiodontitis." (PMID 29109737, 2017).
staphylococcus aureus pneumonia (1 paper, 2018). An pneumonia caused by infection with Staphylococcus aureus. "Furthermore, evidence from an in vivo Staphylococcus aureus pneumonia mouse model suggests that CLCA1 may also modify BPIFA1 expression in airway epithelial cells." (PMID 29610986, 2018).
infection (30 papers, 2010 to 2024). The state of being infected such as from the introduction of a foreign agent such as serum, vaccine, antigenic substance or organism. "Among other changes, this identified a significant upregulation of Scgb1a1 and Bpifa1 expression that was not only associated with expression of M3 but also with MHV-68 infection in general." (PMID 25531566, 2015). "Our results provide insight into the molecular mechanisms underlying the function of BPIFA1, which is modulated by the immune response and can be counteracted in a persistent infection in host airways." (PMID 26646664, 2015). "As part of a study to identify transcriptional signatures associated with the MHV-68 M3 protein during infection, we identified a modulation of Scgb1a1 and Bpifa1 expression." (PMID 25531566, 2015). "Upregulation of many genes associated with activation of innate immunity and SARS CoV-2 disease severity were identified during acute (4 dpi) SARS-CoV-2 (Delta variant) infection in cats, such as KIF11, IRF7, OAS1, BATF2, IF16, and BPIFA1." (PMID 35746678, 2022). "Reducing inflammation of the nasal epithelium is another strategy to protect BPIFA1 from inhibition mediated by infection or injury." (PMID 30255091, 2018). "Bpifa1 mRNA was significantly decreased in the trachea of S. aureus-infected WT mice compared to PBS-treated controls 24 h post-infection." (PMID 29610986, 2018). "Another critical protein, lactoferrin, has been shown to recover expression of BPIFA1 after LPS-induced infection and is a safe, established product utilized in the treatment of various human diseases." (PMID 30255091, 2018). "Quantitative analysis showed that BPIFA1 levels were decreased in bronchioles at day 7 p.i. but increased throughout the entire respiratory tract in response to infection at day 14 p.i.." (PMID 25531566, 2015). "Further analysis of MHV-68-infected animals showed that the levels of both protein and RNA for SCGB1A1 and BPIFA1 were decreased at day 7 post infection (p.i.)but increased at day 14 p.i. as compared with M3-deficient and mock-infected animals." (PMID 25531566, 2015). "Anatomical and temporal changes in Bpifa1 RNA and BPIFA1 protein expression following MHV-68 infection were similarly determined in the same wood mice used for SCGB1A1 analysis." (PMID 25531566, 2015). "The pattern of expression of airway surface liquid (ASL) homeostasis-associated genes (CFTR, BPIFA1, MUC1, MUC5AC, MUC5B) in the PCLS varied greatly between the three strains, and only infection with strain T15 induced statistically significant changes in this group of genes." (PMID 38276150, 2023). "BPIFA1 is a secreted protein that has a protective role during infection." (PMID 32054169, 2020). "BPIFA1 (SPLUNC1), which is abundant in the mammalian nasal, oral, and respiratory mucosa, has broad-spectrum antimicrobial activity and can act as a chemoattractant that recruits macrophages and neutrophils to the site of infection." (PMID 32117425, 2019). "A significantly higher percentage of BPIFA1-positive respiratory epithelial cells per 100 μm basement membrane was observed at 48 h after infection in Clca1−/− mice compared to WT mice in the distal trachea with 22.6 and 14.5% BPIFA1-expressing epithelial cells, respectively (p < 0.05)." (PMID 29610986, 2018). "Although this data was suggestive of an effect of loss of Bpifa1 on infection these differences did not achieve statistical significance." (PMID 29449589, 2018). "In turn, the increased levels of BPIFA1 protein that we observed throughout the entire respiratory tract at day 14 p.i. may indicate a distinct role in the resolution of infection." (PMID 25531566, 2015). "Therefore, nasal steroid sprays can recover BPIFA1 expression in the nasal mucosa and enhance the nasal epithelial innate immune response against LPS-related infection." (PMID 26646664, 2015).
infection (continued). "Cells were allowed to differentiate for 14 to 21 days prior to infection, and differentiation was confirmed by the endpoint PCR of differentiation markers MUC5AC, CBE1, SCGB1A1, BPIFA1 and TEKT1." (PMID 39772226, 2024). "Moreover, Clca1−/− mice infected with S. aureus had significantly higher numbers of BPIFA1-expressing respiratory epithelial cells 48 h after infection when compared to WT mice, arguing that modulation of BPIFA1 expression by respiratory epithelial cells may also be dependent on CLCA1." (PMID 29610986, 2018). "Taken together, the data suggested that deletion of Bpifa1 does not lead to spontaneous development of OM and does not lead to an increased ME infection or overt induction of OM following NTHi inoculation." (PMID 29449589, 2018). "After infection, we detected Bpifa1 RNA in non-ciliated epithelial cells in the trachea, bronchi, and proximal bronchioles but not terminal bronchioles." (PMID 25531566, 2015).
bacterial infection (17 papers, 2010 to 2025). "Patients with decreased BPIFA1 secretion are susceptible to bacterial infections of the upper airway, including those caused by Haemophilus influenzae, Klebsiella pneumoniae, and Pseudomonas aeruginosa." (PMID 26646664, 2015). "We then scored the association between BPIFA1 and IL-13 expression levels in patients with bacterial infection." (PMID 26646664, 2015). "From birth onwards BPIFA1 is secreted at high levels into a film that overlies the epithelium lining the ME, but its absence does not predispose to spontaneous OM or increase the susceptibility to bacterial infection." (PMID 29449589, 2018). "Patients with lower BPIFA1 expression were found to be more susceptible to sinus infection by certain bacterial infection, which may explain this phenomenon." (PMID 30255091, 2018). "As the development of OM is often associated with bacterial infection, we investigated whether the loss of BPIFA1 modulated the ability of mice to respond to the intranasally (IN) inoculated otopathogen NTHi." (PMID 29449589, 2018). "However, the molecular mechanisms underlying IL-13 perturbation of bacterial infection and BPIFA1 expression in host airways require further exploration." (PMID 26646664, 2015). "Downregulation of BPIFA1 was shown to produce an immune defect that rendered the host more susceptible to bacterial infection, thus indicating that reduced SPLUNC1 expression might facilitate recurrent Staphylococcus aureus and Pseudomonas aeruginosa infections in patients with CRSwNP." (PMID 30255091, 2018). "Bpifa1 expression was increased 3.3-fold in stimulated wild type macrophages, and the gene product (SPLUNC1) has a protective role in bacterial infections." (PMID 40238852, 2025). "The focus of this article was the secretory protein, BPIFA1, which plays a key role in the regulation of airway surface liquid volume and serves in host defense against bacterial infection." (PMID 30255091, 2018). "Mechanistically, BPIFA1 contributes to the innate immune response by directly binding to LPS and yielding a bactericidal or bacteriostatic effect against various bacterial infections, an anti-biofilm function, and surfactant properties." (PMID 30255091, 2018). "Although this study has established a cell-based model to demonstrate that IL-13 suppresses BPIFA1 expression in CRSwNP patients with bacterial infections, some limitations are evident." (PMID 26646664, 2015). "Conversely, the level of BPIFA1 expression was markedly reduced in tissues with bacterial infection and expressing a high level of IL-13 as compared to that in tissues without IL-13 expression." (PMID 26646664, 2015). "This evidence indicated that decreased levels of BPIFA1 might facilitate bacterial infection in a host, leading to severe disease manifestations." (PMID 30255091, 2018). "Moreover, the immunohistochemical analysis showed that IL-13 prominently suppressed BPIFA1 expression in eosinophilic CRSwNP patients with bacterial infection." (PMID 26646664, 2015). "In this study, we showed that IL-13 suppresses BPIFA1 secretion from nasal epithelium; hence, it may reduce the innate immune response countering the bacterial infection." (PMID 26646664, 2015). "Reduced BPIFA1 expression may contribute to the persistent nature of bacterial infections in airways, suggesting that BPIFA1 may serve as a host defense protein against bacterial infection." (PMID 26646664, 2015). "Therefore, further investigation is required to clarify the link between IL-13 production and BPIFA1 expression in other types of CRSwNP patients with bacterial infections to provide an opportunity to develop novel strategies to improve therapeutic outcomes." (PMID 26646664, 2015). "However, BPIFA1 expression of grades 0, 1, 2, and 3 was observed in 0, 1, 2, and 3 CRSwNP patients with bacterial infection, respectively." (PMID 26646664, 2015).
bacterial infection (continued). "This evidence indicated that decreased BPIFA1 expression might facilitate bacterial infection in a host, leading to severe disease manifestations." (PMID 26646664, 2015). "However, in NDM subjects, the changes in salivary BPIFA1 might be mainly attributed to local immune responses to bacterial infection." (PMID 29109737, 2017). "However, the molecular mechanism of IL-13 perturbation of bacterial infection and BPIFA1 expression in host airways remains unclear." (PMID 26646664, 2015). "All CRSwNP patients without bacterial infection showed neither BPIFA1 nor IL-13 expression." (PMID 26646664, 2015).
cancer (10 papers, 2008 to 2025). A tumor composed of atypical neoplastic, often pleomorphic cells that invade other tissues. "Moreover, SPARC-like protein 1 (SPARCL1), IQGAP1, BPIFA1, and cornulin are potential candidate proteins abnormally expressed in multiple types of cancers, especially LC." (PMID 36064415, 2022).
BPIFA1 also shares sentences with these, for which no sentence is quoted: tumor (17 papers); respiratory infections (4); chronic lung disease (3); pneumonia (3); adenocarcinoma (2); allergic disease (2); breast carcinoma (2); chronic rhinosinusitis with nasal polyps (2); hepatocellular carcinoma (2); idiopathic pulmonary fibrosis (2); inflammation (2); mucoepidermoid carcinoma (2); non-small cell lung carcinoma (2); otitis (2); squamous cell carcinoma (2); allergic asthma (1); Allergy (1); bronchial pneumonia (1); bronchiectasis (1); cardiomyopathy (1); chronic otitis media (1); ectodermal dysplasia (1); esophagus cancer (1); fibrosis (1); gastric cancer (1); gram-negative bacterial infections (1); hepatoid adenocarcinoma (1); hypohidrotic ectodermal dysplasia (1); Klebsiella pneumonia (1); meningococcal infection (1).
A further 11 diseases each share a sentence with BPIFA1 in 1 paper.